FTO (FTO alpha-ketoglutarate dependent dioxygenase)
Diseases named in the same sentence as FTO in open-access papers (continued):
Sharing a sentence is not in itself a finding about the gene and the disease.
diabetes (continued). "This suggests that the upregulation of FTO in retinal endothelial cells and pericytes may exacerbate diabetes-induced vasculopathy." (PMID 41315216, 2025). "Additionally, endothelial cell-specific deletion of FTO attenuated retinal vascular endothelial dysfunction and inflammation against streptozotocin-induced diabetes in mice." (PMID 38706718, 2024). "Disturbed lactate homeostasis in retina is a common feature of DR, we thus aimed to ascertain whether lactate is responsible for the diabetes-driven FTO up-regulation." (PMID 38297099, 2024). "FTO silencing could alleviate diabetes-related retinal vascular dysfunction and inflammation both in vivo and in vitro by inhibiting NF-κB pathway." (PMID 39296713, 2024). "Combined RNA-Seq and MeRIP-Seq analyses predicted 43 differentially expressed genes in diabetes, and 12 of them may serve as a direct effector of FTO." (PMID 37781923, 2023). "Through genome-wide association meta-analyses of more than 100000 individuals of European ancestry without diabetes, FTO rs1421085 SNP was found to be significantly associated with fasting insulin levels." (PMID 37416800, 2023). "The results revealed aberrant m6A depletion, accompanied by excessive FTO in diabetes." (PMID 37781923, 2023). "In diabetes, excessive FTO downregulates TNIP1, a central regulator of inflammation, thereby activating NF-κB and subsequently increasing inflammatory cytokines (IL-1β and IL-18) in an m6A-dependent manner, ultimately leading to vascular endothelial dysfunction." (PMID 37781923, 2023). "FTO is a main m6A demethylase and has been reported to be involved in diabetes and kidney diseases." (PMID 36792603, 2023). "Interaction analyses of the FTO gene variant rs8050136, gravidity, and GDM revealed significant changes in odd ratios under all genetic models except for the recessive model, when adjusted for family history of diabetes." (PMID 38033012, 2023). "The frequency distributions of FTO rs9939609 polymorphic A allele were estimated at 19.4 and 10.1% in the individuals with a familial history of diabetes and those without the history, respectively (P = 0.024)." (PMID 31200723, 2019). "We investigated if the FTO rs9939609 associates with food preferences in healthy adults with no cancer, cardiovascular disease, or diabetes." (PMID 23589710, 2013). "A fatness-independent association between the FTO rs9939609 A-allele and hs-CRP was observed in a recent German study, and the effect was persistent even when prevalent myocardial infarction, stroke and diabetes were taken into account." (PMID 21246032, 2011). "Therefore, targeting FTO provides new insights into the treatment of diabetes." (PMID 39296713, 2024). "Therefore, we speculate that high fat diet-induced T2DM is secondary to FTO downregulation, which is a protective mechanism in organisms; however, the role of FTO in the CNS of patients with diabetes remains to be investigated." (PMID 38396669, 2024). "Indeed increased body weight in siblings of rats from obese mothers fed HFD may explain the reduction in glucose tolerance compared to those eating standard chow as in humans the link between FTO SNPs and diabetes was abolished by BMI adjustment." (PMID 21980407, 2011). "An example is the link between high‐fat diets and specific genetic variations, such as those in the FTO and TCF7L2 genes, which make a person more likely to develop diabetes." (PMID 41019177, 2025). "Endothelial cell-specific FTO knockout mice exhibit protection against DR, and sustained expression of TNIP1 through AAV-mediated gene therapy significantly mitigates diabetes-induced endothelial dysfunction." (PMID 41315216, 2025). "Another study found that NR3C1 enhancement up-regulated FTO protein levels in β-cells and that the specific FTO inhibitor Dac51 effectively rescued NR3C1-induced β-cell failure, hyperglycemia, and glucose intolerance in diabetes models." (PMID 41585810, 2025).
diabetes (continued). "FTO-mediated RNA demethylation of TNIP1 activates NF-κB, thus accelerating diabetes-induced vascular endothelial dysfunction." (PMID 37781923, 2023). "The results revealed upregulated FTO, accompanied by decreased TNIP1 and elevated NF-κB (p105/p50) levels in EC Ftofl/fl mice with diabetes, whereas in EC FtoΔ/Δ mice, upregulated TNIP1 with suppressed NF-κB was observed." (PMID 37781923, 2023). "In patients with type 2 diabetes (T2D), m6A levels were reduced, while the mRNA levels of FTO, METTL3, METTL14, WTAP were significantly elevated and involved in the pathogenesis of diabetes." (PMID 34026872, 2021). "We found 15 differentially-expressed genes among 20 RNA m6A methylation regulators, including EIF3C, FTO, METTL3, RBM15, etc; and 40 differentially-expressed genes among 46 diabetes related factors." (PMID 34084770, 2021). "Although FTO’s role in DR has not been annotated before, its involvement in diabetes and glucose metabolism has been widely discussed." (PMID 38297099, 2024). "To date, the fundamental role of FTO as a demethylase in diabetes-induced vascular endothelial dysfunction has not been reported to our knowledge." (PMID 37781923, 2023). "Similarly, it is reported that METTL3, FTO, METTL14, and WTAP are up-regulated in diabetes patients." (PMID 33748197, 2021). "The relationship of Omentin Val 109 Asp and FTO rs9939609 genetic variations with newly diagnosed diabetes is not well determined yet." (PMID 31200723, 2019). "In summary, in our case-control study we showed a gender specific association of FTO with AVS independent of BMI, diabetes mellitus and other co-variables." (PMID 26431034, 2015). "Lastly, the association between FTO and AVS was independent of BMI and other variables such as diabetes mellitus." (PMID 26431034, 2015). "There was a significant difference in the four FTO genotype frequencies between diabetes cases and non-cases found for whites, but a difference was only revealed for rs1421085 in African-Americans with the frequency of the minor allele higher in non-cases than in cases." (PMID 20502638, 2010). "We speculate that the downregulation of FTO observed in DN samples relative to normal (NOR) controls may be a consequence of chronic hyperglycemia and oxidative stress, which are hallmark features of diabetes." (PMID 40356725, 2025). "Therefore, the up-regulation of FTO in DM and its negative effect on osteogenesis may play a role in the progression and treatment of periodontitis with diabetes." (PMID 37925419, 2023). "A more recent study on genome-wide DNA methylation of pancreatic islets showed that DNA methylation patterns of T2D candidate genes, including the TCF7L2, FTO and HHEX, were altered in human islets from patients with T2D compared to controls without diabetes." (PMID 28067832, 2017). "We compared FTO expression in vitreous fibrovascular membranes (FVMs) obtained from PDR patients and epi-retinal membranes (ERMs) isolated from age matched controls without diabetes." (PMID 38297099, 2024).
acute myeloid leukemia (146 papers, 2017 to 2025). Acute myeloid leukemia (AML) is a group of neoplasms arising from precursor cells committed to the myeloid cell-line differentiation. "The fat mass and obesity-associated protein (FTO), an RNA N6-methyladenosine (m6A) eraser, has been identified as an oncogenic factor in acute myeloid leukemia (AML)." (PMID 40815637, 2025). "For example, FTO (fat mass and obesity-associated protein) the major m6A eraser, i.e., demethylase, is highly expressed in multiple acute myeloid leukemias, thereby enhancing oncogene-mediated cell transformation and leukemogenesis." (PMID 38769304, 2024). "More recent studies confirmed that FTO was associated with an oncogenic effect in acute myeloid leukemias (AML)." (PMID 35628623, 2022). "Recent studies demonstrated that loss of METTL3, METTL14, or FTO weakens acute myeloid leukemia (AML) propagation, whereas inactivation of METTL3 and METTL14 has deleterious consequences for normal HSC maintenance." (PMID 33156926, 2021). "Besides, the m6A “eraser”, fat mass- and obesity-associated protein (FTO), was found to act as oncogene in acute myeloid leukemia and lung squamous cell carcinoma." (PMID 32111213, 2020). "Increased expression of FTO enhances tumorigenesis of breast cancer as well as acute myeloid leukemia (AML), and is associated with poor prognosis of gastric cancer patients." (PMID 31847302, 2019). "Illustratively, the aberrant activities of m6A-regulatory enzymes like METTL3 and FTO have emerged as potential therapeutic targets in acute myeloid leukemia." (PMID 40724951, 2025). "For example, inhibiting METTL3 expression reduces the proliferation and survival of leukemia cells, while FTO inhibitors show therapeutic potential for acute myeloid leukemia." (PMID 40724951, 2025). "This is similar to the findings of the studies above on the pathogenesis of acute myeloid leukemia, which confirmed FTO as an oncogenic factor in colon cancer." (PMID 39820532, 2025). "Core components of the m6A machinery, including METTL3, METTL14, FTO, and ALKBH5, have been implicated in acute myeloid leukemia (AML) pathogenesis." (PMID 40973767, 2025). "These inhibitors promote differentiation and apoptosis of acute myeloid leukemia (AML) cells by mimicking FTO depletion and enhancing CD8-positive T-cell immune functions." (PMID 40747121, 2025). "The RNA demethylase FTO has been proposed to promote acute myeloid leukemia (AML) by demethylating N6-methyladenosine (m6A) from oncogenic transcripts, especially MYC." (PMID 41279954, 2025). "As the most common and fatal types of hematopoietic malignancies, acute myeloid leukemia (AML) is recently reported to aberrantly upregulate FTO expression, especially in AML cases with t(11q23)/MLL‐rearranged chromosomal abnormalities." (PMID 38721006, 2024). "For instance, in acute myeloid leukemia, FTO eradicated the m6A modification from ASB2 and RAR-α mRNAs, leading to their degradation and thus suppressing myeloid differentiation." (PMID 38556586, 2024). "In acute myeloid leukemia, FTO was shown to control stem cell differentiation through the ASB2/RARA axis, and FTO was revealed to affect immunotherapy by regulating intracellular factors (PD-1, CXCR4, and SOX10) in melanoma." (PMID 38384328, 2024). "Inhibition of FTO obstructs cell propagation and migration in acute myeloid leukemia, glioma, and breast cancer." (PMID 39449798, 2024). "In 2017, for the first time, researchers revealed that FTO can play a crucial oncogenic role in acute myeloid leukemia (AML)." (PMID 39468015, 2024). "Dysregulation of FTO is observed in various cancers, including acute myeloid leukemia (AML), glioblastoma, cervical squamous cell carcinoma (CSCC), gastric cancer, and small cell lung cancer." (PMID 39192357, 2024). "In acute myeloid leukemia, FTO was directly defined as an oncogene when it played a m6A RNA demethylase role." (PMID 37840133, 2023).
acute myeloid leukemia (continued). "FTO has been suggested to play a tumorigenic role in acute myeloid leukemia, while inhibition of FTO exerts an extensive anti‐leukemic activity in vitro and in vivo." (PMID 36794620, 2023). "Other studies also reported apoptotic cell death in acute myeloid leukemia cells treated with FTO shRNA17 and GC1 spermatogonia cell line treated with meclofenamic acid as FTO inhibitor." (PMID 36534072, 2023). "FTO is upregulated and exhibits a tumor-promoting role in the majority of cancer types, including acute myeloid leukemia (AML), breast cancer, liver cancer, gastric cancer and colorectal cancer." (PMID 37919739, 2023). "The demethyltransferase FTO has been found to exert a pro-carcinogenic effect in acute myeloid leukemia by regulating m6A levels on the mRNA of downstream target genes, such as ASB2 and RARA22." (PMID 37576401, 2023). "FTO, the first identified “eraser” of m6A, has been reported to be highly expressed in acute myeloid leukemia (AML) subtypes and to promote AML development." (PMID 36497402, 2022). "The pathological role of FTO as an m6A demethylase in cancer was first reported in acute myeloid leukemia, and FTO inhibitor R-2-hydroxyglutarate exerts tumor-suppressive activity by targeting FTO/C-Myc/CEBPA pathway, revealing great clinical value." (PMID 35311620, 2022). "For instance, FB23-2, an m6A-RNA demethylase FTO inhibitor, impairs acute myeloid leukemia cell proliferation and induces apoptosis." (PMID 36439881, 2022). "More importantly, FB23-2 dramatically inhibited the progression of human acute myeloid leukemia cell lines and primary cells in xenografted mice 6, highlighting the broad potential of targeting FTO for cancer therapy." (PMID 36263177, 2022). "Upregulated expression of FTO intrinsically modulates genes in tumor cells that relate to malignant potential, promoting the progression of various types of cancer such as acute myeloid leukemia (AML), glioblastoma (GBM), CRC, and GC." (PMID 35296338, 2022). "Saikosaponin-d also exhibited antileukemic activity by targeting FTO/m6A signaling in human acute myeloid leukemia cells in vitro." (PMID 36120320, 2022). "In this study, R-2HG was used to directly inhibit FTO in R-2HG-sensitive acute myeloid leukemia and glioma cells, leading to increased methylation and decreased expression of c-MYC and CEBPA mRNAs, thereby enhancing the anti-tumor effects." (PMID 34124065, 2021). "FTO plays an oncogene role in early acute myeloid leukemia, lung cancer, and cervical cancer and plays a tumor suppressor gene role in hepatocellular carcinoma and thyroid cancer." (PMID 33952279, 2021). "FTO was first identified to be a tumor-promoting factor in acute myeloid leukemia as an m6A demethylase." (PMID 34544449, 2021). "In in vitro experiments, the FTO inhibitor FB23-2 reduced the expression of FTO and significantly inhibited the proliferation of human acute myeloid leukemia primary cells." (PMID 34858499, 2021). "As an important demethylase, FTO has been identified to play an oncogenic role in NSCLC, ovarian cancer, and acute myeloid leukemia, associating with cancer cell proliferation, cancer stem cell maintenance and other malignant characteristics." (PMID 35004679, 2021). "FTO played an oncogenic role in acute myeloid leukemia through regulating target genes such as ASB2 and RARA by reducing m6A levels in these mRNA transcripts." (PMID 32111213, 2020). "These include acute myeloid leukemia through promoting leukemogenesis via FTO-mediated m6A demethylation of core transcripts as ASB2 and RARA mRNAs promoting decreased stability of the target transcripts." (PMID 33511112, 2020). "FTO acted as an oncogene in acute myeloid leukemia (AML) through regulating target genes such as ASB2 and RARA by reducing m6A levels in these mRNA transcripts." (PMID 32209098, 2020).
acute myeloid leukemia (continued). "The up-regulation of WTAP was able to promote the proliferation and survival of tumor cells, while FTO plays an oncogenic role as an m6A demethylase in acute myeloid leukemia." (PMID 32500031, 2020). "FTO was demonstrated to promote the proliferation, transformation and survival of acute myeloid leukemia cells in vivo and in vitro." (PMID 32038982, 2020). "FTO regulates leukemogenesis by modulating proliferation, differentiation and apoptosis of acute myeloid leukemia (AML) cells." (PMID 31801551, 2019). "Two independent previous studies stated that both METTL3 and FTO played an oncogenic role in acute myeloid leukemia through the diverse downstream targets." (PMID 31230592, 2019). "FTO is highly expressed in acute myeloid leukemia and can inhibit the differentiation of acute myeloid leukemia cells induced by all-trans retinoic acid." (PMID 31808521, 2019). "For m6A demethylases, previous studies have suggested that FTO has an oncogenic role in acute myeloid leukemia." (PMID 30953473, 2019). "Previous study reported that FTO was highly expressed and functioned as an oncogene in certain subtypes of acute myeloid leukemia (AML) by targeting ASB2 and RARA through mRNA demethylation." (PMID 31143705, 2019). "FTO, as m6A “erasers”, has also been reported to have pro‐tumorigenic function in acute myeloid leukaemia and glioblastoma, but we show that FTO plays a critical anti‐tumorigenic role in ccRCC." (PMID 30648791, 2019). "Overexpression of FTO in some acute myeloid leukemia (AML) also affects the m6A levels in certain mRNA transcripts that further promote leukemogenesis." (PMID 30654440, 2019). "While some studies have focused on inhibiting FTO in certain cancers where it functions as an oncogene, such as in acute myeloid leukemia, our data clearly position FTO as a protective factor in the context of glioma, where its loss contributes to disease progression." (PMID 40970086, 2025). "FTO degrader impairs ribosome biogenesis in acute myeloid leukemia." (PMID 40815637, 2025). "FTO induced cell transformation by proto-oncogenes and resulted in acute myeloid leukemia." (PMID 39867638, 2025). "FTO is not only involved in obesity-related diseases, but it also plays a critical role in neurodegenerative disorders and various cancers, such as lung cancer, gastric cancer, acute myeloid leukemia, and melanoma." (PMID 37781923, 2023). "Moreover, another study indicated that R-2-hydroxyglutarate produced at high levels by mutant isocitrate dehydrogenase 1/2 enzymes exhibited anticancer effects by suppressing FTO activity, thereby increasing m6A levels in acute myeloid leukemia (AML) cells." (PMID 36632456, 2023). "For example, the high expression of FTO may lead to leukemic cell transformation and tumorigenesis in acute myeloid leukemia, and it is observed that the expression of FTO and METTL3 were upregulated in renal clear cell carcinoma." (PMID 36051357, 2022). "Earlier studies showed that FTO is not only expressed in STAD, but also in acute myeloid leukemia, cervical squamous carcinoma, and glioblastoma, indicating that FTO may be involved in the development of other tumors." (PMID 35299934, 2021). "Researchers have proven that FTO promotes cell proliferation of acute myeloid leukemia." (PMID 33314339, 2021). "Thereafter, FTO was shown to direct gene expression by changing the level of mRNA m6A methylation and acts as an oncogene in breast cancer, lung cancer, endometrial cancer, acute myeloid leukemia as well as pancreatic cancer." (PMID 33461172, 2021). "It was found to impede FTO in a way mimicking FTO depletion in acute myeloid leukemia cell lines." (PMID 33511112, 2020). "As a m6A RNA demethylase, FTO is highly expressed in acute myeloid leukemia." (PMID 31131257, 2019). "Another recent publication shed light on the role of FTO in acute myeloid leukemia (AML)." (PMID 29125541, 2017).